SUN3 (Sad1 and UNC84 domain containing 3)
Description:
As a probable component of the LINC (LInker of Nucleoskeleton and Cytoskeleton) complex, involved in the connection between the nuclear lamina and the cytoskeleton. The nucleocytoplasmic interactions established by the LINC complex play an important role in the transmission of mechanical forces across the nuclear envelope and in nuclear movement and positioning. May be involved in nuclear remodeling during sperm head formation in spermatogenesis. A probable SUN3:SYNE1 LINC complex may tether spermatid nuclei to posterior cytoskeletal structures such as the manchette.
Synonyms: SUNC1; MGC33329
Tractability: Antibody: UniProt predicts a signal peptide or a membrane-spanning region; the Human Protein Atlas places it where antibodies can reach.
Gene: Protein-coding gene on chromosome 7 (47,987,148 to 48,029,119, reverse strand). Ensembl gene ENSG00000164744.
Subcellular location: Membrane; Nucleus envelope; Nucleus inner membrane
Subcellular location (Human Protein Atlas): Nucleoplasm; Plasma membrane
Gene Ontology:
Cellular component: meiotic nuclear membrane microtubule tethering complex; nuclear envelope; membrane; nuclear inner membrane
Genetic constraint (gnomAD): Loss-of-function variants: 21 observed, 25.33 expected, observed/expected ratio (o/e) 0.83, 90% interval 0.59 to 1.19. The upper end of that interval is the gene's LOEUF score, 1.19, which puts it in group 5 of 6, group 1 being the genes least tolerant of losing a copy. Missense variants: 275 observed, 294.66 expected, observed/expected ratio (o/e) 0.93, 90% interval 0.85 to 1.03. Synonymous variants: 99 observed, 103.57 expected, observed/expected ratio (o/e) 0.96, 90% interval 0.81 to 1.13.
Homologues: Orthologues: chimpanzee SUN3 (99% identical), macaque SUN3 (94% identical), pig SUN3 (79% identical), dog SUN3 (78% identical), rabbit SUN3 (73% identical), rat Sun3 (73% identical), mouse Sun3 (72% identical), chimpanzee SUN3 (71% identical), guinea pig SUN3 (65% identical), Caenorhabditis elegans unc-84 (23% identical). Paralogues in human: SUN2 (34% identical), SUN1 (34% identical), SUN5 (25% identical), SPAG4 (24% identical).
Diseases named in the same sentence as SUN3 in open-access papers:
SUN3 is named in the same sentence as 1 disease in open-access papers, as found by Europe PMC text mining. Sharing a sentence is not in itself a finding about the gene and the disease. The quoted sentences say what the papers report.
Arthritis (1 paper, 2022). Inflammation of a joint. "SUN3 is also overexpressed in arthritis and is a potential marker molecule for arthritis." (PMID 36421827, 2022).